RGS17 (regulator of G protein signaling 17)
Description:
Regulates G protein-coupled receptor signaling cascades, including signaling via muscarinic acetylcholine receptor CHRM2 and dopamine receptor DRD2. Inhibits signal transduction by increasing the GTPase activity of G protein alpha subunits, thereby driving them into their inactive GDP-bound form. Binds selectively to GNAZ and GNAI2 subunits, accelerates their GTPase activity and regulates their signaling activities. Negatively regulates mu-opioid receptor-mediated activation of the G proteins (By similarity).
Synonyms: RGSZ2; RGS-17; hRGS17
Tractability: Small molecule: a high-quality ligand is known. Antibody: its Gene Ontology location is reachable by antibodies, with high confidence. PROTAC: UniProt records ubiquitination sites on it; a small molecule that binds it is known.
Gene: Protein-coding gene on chromosome 6 (153,004,459 to 153,131,282, reverse strand). Ensembl gene ENSG00000091844.
Subcellular location: Membrane; Synapse, synaptosome; Nucleus; Cytoplasm
Subcellular location (Human Protein Atlas): Vesicles
Pathways (Reactome):
Signal Transduction: G alpha (i) signalling events; G alpha (q) signalling events; G alpha (z) signalling events
Gene Ontology:
Molecular function: protein binding; GTPase activity
Biological process: G protein-coupled receptor signaling pathway; negative regulation of G protein-coupled receptor signaling pathway; response to amphetamine
Cellular component: cytoplasmic side of plasma membrane; plasma membrane; cytoplasm; membrane; nucleus; synapse
Genetic constraint (gnomAD): Loss-of-function variants: 3 observed, 10.95 expected, observed/expected ratio (o/e) 0.27, 90% interval 0.12 to 0.71. The upper end of that interval is the gene's LOEUF score, 0.71, which puts it in group 2 of 6, group 1 being the genes least tolerant of losing a copy. Missense variants: 93 observed, 126 expected, observed/expected ratio (o/e) 0.74, 90% interval 0.62 to 0.88. Synonymous variants: 44 observed, 42.04 expected, observed/expected ratio (o/e) 1.05, 90% interval 0.82 to 1.35.
Homologues: Orthologues: chimpanzee RGS17 (100% identical), macaque RGS17 (100% identical), dog RGS17 (98% identical), rabbit RGS17 (98% identical), guinea pig RGS17 (97% identical), pig RGS17 (97% identical), rat Rgs17 (94% identical), mouse Rgs17 (92% identical), tropical clawed frog rgs17 (88% identical), zebrafish rgs17 (61% identical), Drosophila melanogaster Dhit (53% identical). Paralogues in human: RGS20 (63% identical), RGS19 (54% identical), RGS3 (38% identical), RGS18 (30% identical), RGS11 (29% identical), RGS12 (29% identical), RGS21 (29% identical), RGS6 (29% identical), RGS7 (29% identical), RGS5 (29% identical), RGS16 (28% identical), RGS4 (28% identical), and 11 more.
Diseases named in the same sentence as RGS17 in open-access papers:
RGS17 is named in the same sentence as 28 diseases in open-access papers, as found by Europe PMC text mining. Sharing a sentence is not in itself a finding about the gene and the disease. The quoted sentences say what the papers report.
lung carcinoma (9 papers, 2010 to 2024). "The expression of miR-182 is downregulated in lung cancer and is correlated with upregulated expression of RGS17." (PMID 32913477, 2020). "Increased expression of RGS17 in prostate and lung cancers has been shown to support cancer progression." (PMID 27105500, 2016). "For example, miR-182 was reported to suppress lung tumorigenesis and lung cancer cell proliferation through downregulation of RGS17 or RASA1." (PMID 26338969, 2015). "Significantly, abnormal expression of multiple RGS proteins, such as RGS17 in hepatocellular carcinoma, lung cancer, and prostate cancer, RGS5 in ovarian cancer and squamous cell carcinoma, and RGS6 in breast cancer and urinary bladder cancer, has been documented in relation to tumor progression." (PMID 38906869, 2024). "An example of such a genetic effect is represented by the RGS17 gene on Chr 6q24 implicated in familial lung cancer but not investigated here." (PMID 21304900, 2011). "In lung cancer cells, RGS17 proliferative effects are mediated by cAMP activation of PKA and CREB." (PMID 21044322, 2010). "Regulator of G protein signaling 17 (RGS17) stimulates cell proliferation through the cAMP–PKA–CREB pathway, which is elevated in 80% of lung cancer tissues relative to matched normal lung tissue." (PMID 35805104, 2022). "However, some studies recognized miR-182-5p as an inhibitor of the process of proliferation; indeed, miR-182-5p downregulates the mRNA products for proteins promoting the cancer development, including CTTN, RGS17, and CREB1 in ovarian papillary carcinoma, gastric adenocarcinoma, and in lung cancer." (PMID 36980984, 2023).
prostate carcinoma (8 papers, 2010 to 2024). A carcinoma that arises from epithelial cells of the prostate gland. "Strikingly, RGS17 expression showed the highest level in prostate cancer among tens of different cancer types in over 10,000 tumor samples, further supporting that RGS17 is a plausible prostate cancer susceptibility gene." (PMID 29789573, 2018). "Based on our prostate tissue eQTL analysis, allele A significantly downregulated target gene RGS17, consistent with the protective effect of GWAS risk SNP on prostate cancer." (PMID 29789573, 2018). "Furthermore, we performed in depth evaluation on the regulatory role of two prostate cancer-risk loci and provided strong evidence showing essential role of RGS17 for the maintenance of the proliferative potential of tumor cells." (PMID 29789573, 2018). "RGS17 has been reported to induce lung and prostate cancer proliferation via the cAMP-PKA-CREB pathway." (PMID 38431606, 2024). "However, RGS17 exerts positive effects on cancer cell growth in lung cancer, prostate cancer and hepatocellular carcinoma." (PMID 37118788, 2023). "Furthermore, by querying prostate cancer datasets, we found that RGS17 was up-regulated in prostate adenocarcinoma." (PMID 29789573, 2018). "Notably, our results are in contrast with a recent study showing that RGS17, which is overexpressed in human lung and prostate cancer, induces tumor cell proliferation." (PMID 21044322, 2010). "In particular, through methods such as high-throughput screening, many studies have identified RGS17 as a new target in lung and prostate cancers, and the specific mechanism may be related to the induction of tumour cell proliferation by RGS17 through regulation of the cAMP-PKA-CREB pathway." (PMID 37924113, 2023). "To test whether downregulation of RGS17 inhibited prostate cancer cell growth, we performed cell proliferation assays in the prostate cancer cells using siRNA against RGS17 and observed greatly reduced cell growth and viability when compared to the cells with control siRNAs." (PMID 29789573, 2018). "Similar phenomena can be also detected in prostate cancer cells, where RGS2 inhibits cell growth with the decreased RGS2 expression while RGS17 enhances cell growth with the increased RGS17 expression." (PMID 37118788, 2023).
ovarian carcinoma (6 papers, 2010 to 2024). A malignant neoplasm originating from the surface ovarian epithelium. "Taken together, our data suggest that chemotherapy exposure triggers loss of RGS10 and RGS17 expression in ovarian cancer cells, and that loss of expression contributes to the development of chemoresistance, possibly through amplification of endogenous AKT signals." (PMID 21044322, 2010). "RGS17 can affect the occurrence and development of ovarian cancer through the PI3K/AKT cellular survival pathway." (PMID 37649067, 2023). "For example, RGS10 and RGS17 knockdown conferred cisplatin-resistance in ovarian cancer cells, whereas increasing RGS17 in nasopharyngeal cancer improves sensitivity to 5-fluorouracil." (PMID 34209775, 2021). "Establishing this important mechanism involving RGS10 and RGS17 is the first part of a systematic evaluation of cellular signaling in ovarian cancer chemoresistance." (PMID 21044322, 2010). "This study introduces RGS10 and RGS17 as novel mediators of chemoresistance in ovarian cancer cells." (PMID 21044322, 2010). "The current study focuses on the role of RGS10 and RGS17 in determining chemoresistance in ovarian cancer cells." (PMID 21044322, 2010). "Our results establish RGS10 and RGS17 as novel regulators of cell survival and chemoresistance in ovarian cancer cells and represents the first link between any RGS protein and cancer chemoresistance." (PMID 21044322, 2010). "In addition to RGS2, other RGS proteins such as RGS5, RGS10 and RGS17 are also closely related to ovarian cancer." (PMID 37649067, 2023). "Finally, we observed that RGS10 and RGS17 are able to suppress LPA-induced activation of the survival factor AKT, suggesting a mechanistic model for RGS10 and RGS17 control of chemoresistance in ovarian cancer cells." (PMID 21044322, 2010). "Our results establish RGS10 and RGS17 as novel regulators of cell survival and chemoresistance in ovarian cancer cells and suggest that their reduced expression may be diagnostic of chemoresistance." (PMID 21044322, 2010). "Taken together, these data show that RGS2, RGS10, and RGS17 transcripts are commonly downregulated in acquired chemoresistance in three distinct ovarian cancer cell lines resistant to three distinct chemotherapeutics, while RGS5 was down-regulated in two of the models." (PMID 21044322, 2010). "However, other Gi-coupled GPCRs are implicated in ovarian cancer proliferation and survival signaling, such as endothelin, chemokine, and prostaglandin receptors, suggesting RGS10 and RGS17 may regulate multiple survival pathways besides LPA." (PMID 21044322, 2010). "The elevation in RGS17 expression resulted in a decrease in AKT activation followed by LPA treatment, thus illustrating the mechanism of growth arrest of ovarian cancer cells and the relevance of RGS17 expression in ovarian cancer cells." (PMID 37649067, 2023). "An obvious candidate survival pathway is the PI3K/AKT pathway, which is activated in ovarian cancer cells via Gi G-proteins, targets of deactivation by RGS10 and RGS17." (PMID 21044322, 2010). "Our observation that inhibition of RGS10 and RGS17 expression enhances cell survival in the presence of chemotherapeutics suggests that endogenous RGS10 and RGS17 may suppress constitutive survival signals in ovarian cancer cells." (PMID 21044322, 2010).
hepatocellular carcinoma (5 papers, 2019 to 2024). A malignant tumor that arises from hepatocytes. "Moreover, miR-199 is also able to suppress the cell proliferation, migration and invasion in hepatocellular carcinoma via the negative regulation of RGS17." (PMID 31386624, 2019).
breast carcinoma (2 papers, 2023 to 2024). "For example, some RGS proteins including RGS4, RGS16, RGS2, RGS6 and RGS17 negatively regulate the progression of breast cancer, whereas RGS20 protein exerts the positive effects on potentiating the carcinogenesis of breast cancer." (PMID 37118788, 2023).
hearing loss (2 papers, 2021 to 2025). "To investigate the role of RGS17 in cisplatin-induced hearing loss model, we administered siRNA against RGS17 via trans-tympanic route (0.9 μg) into the middle ear of male Wistar rats, two days prior to cisplatin treatment." (PMID 33854102, 2021). "In this study we show that cisplatin induces the expression of the RGS17 gene and increases the levels of RGS17 protein which contributes to a significant proportion of the hearing loss." (PMID 33854102, 2021). "To assess whether RGS17 gene deletion in hair cells protects against cisplatin-induced hearing loss, we performed a functional study comparing wild-type mice with inducible hair cell-specific RGS17 knockdown (RGS17+/−) and knockout (RGS17−/−) mice." (PMID 40061942, 2025). "Thus, RGS17 represents a novel mediator of cisplatin ototoxicity and a potential therapeutic target for treating hearing loss." (PMID 33854102, 2021). "Therefore, RGS17 could be a novel target for the amelioration of cisplatin-induced hearing loss." (PMID 40061942, 2025). "Our findings support this proposed mechanism, as RGS17 depletion blocks CXCL1 production in hair cells and protects against cisplatin-induced hearing loss." (PMID 40061942, 2025).
liver cancer (1 paper, 2022). An epithelial or non-epithelial malignant neoplasm that arises from the liver. "To date, 20 canonical RGS genes (RGS1-RGS20) have been reported and a few members of the RGS family (RGS3, RGS5, RGS17) have also been associated with liver cancer." (PMID 36009801, 2022).
ovarian tumors (1 paper, 2010). "Clinical expression data available through the Oncomine database suggests that RGS17 is expressed at significantly lower levels in ovarian tumors compared to normal ovary, with expression of RGS17 progressively decreasing with advancing disease grade." (PMID 21044322, 2010).
prostate neoplasm (1 paper, 2020). A neoplasm (disease) that involves the prostate gland. "The RGS17 locus show associations with various cancers, including PrCa and prostate neoplasm, and body mass index (BMI) but has no known associations with any T2D-related trait (no relevant mouse data available)." (PMID 33290408, 2020).
cancer (13 papers, 2010 to 2025). A tumor composed of atypical neoplastic, often pleomorphic cells that invade other tissues. "Also, RGS17 plays a role in several cellular processes, and it has been linked to certain diseases, including cancer, neurological disorders, and inflammation." (PMID 40076487, 2025). "For example, in ovarian cancer cells RGS17 is found to be involved in the suppression of cancer cell growth and in the elevated responses to certain chemotherapeutic drugs." (PMID 37118788, 2023). "Increased RGS17 expression has been detected in prostate cancer, and knockdown of its expression also results in decreased proliferation of other cancer cells." (PMID 27105500, 2016). "RGS17 acts as a GTPase-activating protein (GAP) by attenuating Gαi/o-mediated cAMP formation which results in the upregulation of protein kinase A signals that promote cancer proliferation, migration, and invasion." (PMID 40061942, 2025). "This means that the compounds found in tarragon essential oils may act as moderate inhibitors of RGS17, potentially having clinical utility as chemotherapeutics in the treatment of several types of cancers." (PMID 40076487, 2025). "The results obtained using molecular docking reveal that the compounds found in tarragon essential oils may act as moderate inhibitors of RGS17 and have potential clinical utility as chemotherapeutics in the treatment of several types of cancers." (PMID 40076487, 2025).
tumor (8 papers, 2010 to 2025). "In opposition to previous studies, a study has indicated that miR-182 can act as a tumor suppressor in LC by regulating the expression of a member of the G protein signaling family regulator encoded by the RGS17 gene." (PMID 37438760, 2023). "Regarding miR-199, previous data showed that this miRNA was associated with cell cycle processes in HCC via XBP1/cyclin D and acted as a tumor suppressor by targeting RGS17 in the inhibition of tumor growth." (PMID 32330203, 2020). "We further demonstrate that RGS10 and RGS17 expression regulates the cellular toxicity of multiple cytotoxic chemotherapeutics, which ultimately enhances the viability of these tumor cells in the presence of chemotherapy." (PMID 21044322, 2010). "Thus, we hypothesize that RGS10 and RGS17 function as tumor suppressors by blunting endogenous survival pathways." (PMID 21044322, 2010). "Decreased expression of RGS17, in addition to inhibiting NSCLC cell proliferation in vitro, diminished in vivo tumor progression." (PMID 37438760, 2023). "Another study reports that miR-199 is a tumor-suppressing miRNA, and its expression is reduced in NSCLC, and miR-199 suppresses the malignant progression of NSCLC via targeting RGS17." (PMID 34193018, 2021).
infection (1 paper, 2021). The state of being infected such as from the introduction of a foreign agent such as serum, vaccine, antigenic substance or organism. "In this study, we found knockdown of CB2 with siRNA significantly increased RGS17 mRNA level by 2.4 ± 0.4-fold and infection of cochleae with adenoviral vector over expressing RGS17 led to significant reductions in CB2 expression to 0.2 ± 0.02 fold." (PMID 33854102, 2021).
inflammation (1 paper, 2025). Aberrant reaction of the microcirculation characterized by movement of fluid and leukocytes from the blood into extravascular tissues. "We speculate that RGS17 activation via cisplatin is one of the mechanisms associated with cochlear inflammation mediated by chemokine/chemokine receptors." (PMID 40061942, 2025).
RGS17 also shares sentences with these, for which no sentence is quoted: bladder cancer (2 papers); Allergy (1); Alzheimer disease (1); cervical cancer (1); colorectal cancer (1); gastric adenocarcinoma (1); nasopharyngeal carcinoma (1); neurological disorders (1); non-small cell lung carcinoma (1); panic disorder (1); prostate adenocarcinoma (1); schizophrenia (1); squamous cell carcinoma (1); substance dependence (1); Type 2 Diabetes (1).